RPPH1 (ribonuclease P RNA component H1)
Synonyms: H1RNA; RPPH1-1
Gene: Gene (Ensembl biotype ribozyme) on chromosome 14 (20,343,075 to 20,343,407, reverse strand). Ensembl gene ENSG00000277209.
Pathways (Reactome):
Metabolism of RNA: tRNA processing in the nucleus
Gene Ontology:
Molecular function: ribonuclease P activity
Biological process: tRNA processing
Cellular component: ribonuclease P complex
Diseases named in the same sentence as RPPH1 in open-access papers:
RPPH1 is named in the same sentence as 27 diseases in open-access papers, as found by Europe PMC text mining. Sharing a sentence is not in itself a finding about the gene and the disease. The quoted sentences say what the papers report.
colorectal cancer (18 papers, 2019 to 2025). A primary or metastatic malignant neoplasm that affects the colon or rectum. "The Rn7sk, Rpph1, Rn7sl1, Rn7sl2, Znf460, Snord17, Snora73b, H1-4, H4c12, and H3c7 genes were discovered to be highly upregulated in the tumor tissue collected from colorectal cancer patients." (PMID 40427657, 2025). "Consistent with our findings, previous studies have shown that LncRNA RPPH1 promotes colorectal cancer metastasis by interacting with TUBB3 and promoting exosome-mediated macrophage M2 polarization." (PMID 38459596, 2024). "Colorectal cancer (CRC) cell exosome-derived lncRNA RPPH1 mediates macrophage M2 polarization, promoting CRC cell metastasis and proliferation." (PMID 39676873, 2024). "For example, RPPH1 promotes colorectal cancer cell metastasis by binding to β-III tubulin (TUBB3) and enhancing M2 macrophage polarization." (PMID 36619232, 2023). "In colorectal cancer, RPPH1 was revealed to boost tumor metastasis by promoting macrophage polarization and therefore associated with poor prognosis." (PMID 37291525, 2023). "Another study has been also revealed colorectal cancer cells-derived exosomal RPPH1 mediates M2 polarization, thus elevated the ability of metastasis of colorectal cancer cells." (PMID 36482354, 2022). "We found that circRNAs derived from ribonuclease P RNA component H1 (RPPH1) were highly expressed in colorectal cancer (CRC) samples from Gene Expression Omnibus (GEO) datasets." (PMID 35155186, 2021). "In colorectal cancer, RPPH1 was also demonstrated to facilitate cancer development and metastasis." (PMID 37291525, 2023). "RPPH1 is a long noncoding RNA and facilitates cancer development of many cancers like esophageal cancer and breast cancer and also receives mediated macrophages to promote the proliferation and metastasis of colorectal cancer." (PMID 35813821, 2022). "Liang et found that exosomal lncRNA RPPH1 could promote colorectal cancer metastasis by triggering macrophage M2 polarization." (PMID 35785218, 2022). "Additionally, recent studies have suggested that TUBB3 upregulates Snail and represses ECAD, and ubiquitination of TUBB3 is blocked by the long noncoding RNA RPPH1 during metastasis of colorectal cancer cells." (PMID 33256003, 2020). "In colorectal cancer (CRC), RPPH1 was significantly upregulated in both tissue and exosomes, and was proposed as a potential therapeutic and diagnostic target, which aligns with our findings regarding its diagnostic potential." (PMID 39925803, 2025). "Mechanistically, RPPH1 binds to TUBB3 to prevent its ubiquitination and then induces EMT in colorectal cancer cells." (PMID 36619232, 2023). "In colorectal cancer (CRC) tissues, RPPH1 induces epithelial-mesenchymal transition (EMT) by preventing ubiquitination of β-tubulin TUBB3 and promotes local macrophage polarization through exosomal transfer of CRC-expressed RPPH1." (PMID 36754845, 2023). "Since cancer cell-derived exosomes contain RPPH1, this lncRNA is able to affect TUBB3 expression in other surrounding cancer cells, encouraging colorectal cancer progression." (PMID 35055115, 2022). "LncRNA RPPH1 was identified to combine with TUBB3 and inhibit its ubiquitination, thus promoting colorectal cancer cells metastasis." (PMID 35541917, 2022). "Furthermore, it was proven that RPPH1 physically binds to and stabilizes TUBB3 proteins in colorectal cancer cells." (PMID 35055115, 2022).
breast cancer (16 papers, 2017 to 2025). A primary or metastatic malignant neoplasm involving the breast. "To explore the molecular mechanism through which RPPH1 contributes to cell proliferation and causes apoptosis in breast cancer cells, we investigated the potential target genes involved in cell proliferation and the cell cycle through microarray analysis." (PMID 29200969, 2017). "Overall, our results demonstrated that RPPH1 functions as a tumour promoter and plays an important role in advancing tumorigenesis by targeting miR-122 and may serve as a novel and potential therapeutic, diagnostic or prognostic target in breast cancer." (PMID 29200969, 2017). "RPPH1 enhances breast cancer progression by stabilizing m6A-modified FGFR2 mRNA via IGF2BP2, activating PI3K/AKT signaling." (PMID 40565315, 2025). "Consistent with and in addition to these reports, a novel circular form of RPPH1, circ-RPPH1, is elevated in breast cancer, cervical cancer, and hepatocellular carcinoma and in all cases promotes proliferation and tumor growth by sequestering specific miRNAs." (PMID 36754845, 2023). "RPPH1 functions as a tumor promoter and plays an important role in advancing tumorigenesis by targeting miR-122 in breast cancer." (PMID 36619232, 2023). "In a report, Zhang and colleagues used shRNA fragments to knock down lncRNA RPPH1 expression in breast cancer cells." (PMID 36230935, 2022). "An inverse correlation between RPPH1 and miR-122 levels in breast cancer tissues and cell lines was observed, and miR-122 overexpression decreased cell proliferation mediated by RPPH1 overexpression." (PMID 32611613, 2020). "RPPH1 overexpression in breast cancer cell lines increased proliferation and colony formation, whereas its knockdown had opposite effects and led to decreased tumor size in nude mice." (PMID 32611613, 2020). "And lncRNA RPPH1 can promote breast cancer cell proliferation and tumorigenesis via down-regulating miR-122 expression." (PMID 31750237, 2019). "In paired clinical samples, breast cancer tissues had up-regulated expression of RPPH1 in comparison to the adjacent normal tissues." (PMID 31645843, 2019). "The level of miR-122 expression had an almost opposite trend with the level of RPPH1 expression in the four kinds of breast cancer cell lines, as well as in the RPPH1 overexpression and knockdown models." (PMID 29200969, 2017). "RPPH1 is one of the lncRNA genes that are expressed differently between breast cancer and normal tissues by the lncRNA gene chip." (PMID 29200969, 2017). "Further evaluation by the MTT assay of lncRNA RPPH1 in the breast cancer cell lines showed that cell proliferation was increased in the overexpressed vector, but suppressed in the knockdown model." (PMID 29200969, 2017). "MiR-122, which has been reported to have a role in cancers, has diverse target genes; we chose seven of these to explore the downstream genes of miR-122 when RPPH1 was overexpressed in breast cancer cells." (PMID 29200969, 2017). "In this study, we first found that lncRNA RPPH1 was significantly upregulated in breast cancer tissues compared with adjacent normal tissues; these findings corresponded with the result of microarray ISH." (PMID 29200969, 2017). "Statistical evaluation of tumour volume showed that the interactions of RPPH1 can decrease the size of breast cancer in nude mice." (PMID 29200969, 2017). "RPPH1 also enhances cell proliferation in breast cancer and AML cell lines by mechanistically antagonizing specific miRNAs, suggesting RPPH1 may function as a molecular miRNA sponge." (PMID 36754845, 2023). "Mechanistically, through exosomes transport into macrophages, RPPH1 derived from breast cancer cells could induce M2 polarization of macrophages." (PMID 33520725, 2020). "In addition, the in vivo study demonstrated that RPPH1 is able to promote the metastasis of breast cancer." (PMID 33520725, 2020).
breast cancer (continued). "Moreover, lentivirus-mediated interference of RPPH1 was further demonstrated to be able to suppress the tumor formation in nude mice inoculated with either human breast cancer MCF-7 cells or AML THP-1 cells." (PMID 31645843, 2019). "Moreover, RPPH1 over-expression was found to promote breast cancer progression through functional suppression of miR-122 and its targets (Zhang and Tang, 2017)." (PMID 31645843, 2019). "Consistently, RPPH1 expression was also found to be involved in the progression of breast cancers." (PMID 31645843, 2019). "Our study was conducted to examine the regulation of lncRNA RPPH1 in breast cancer." (PMID 29200969, 2017). "Based on these results, we assumed that RPPH1 plays an important role in the development of breast cancer and its high expression may help promote tumour deterioration; therefore, RPPH1 may be a promising prognostic biomarker for breast cancer." (PMID 29200969, 2017). "To further explore the functions of RPPH1 in breast cancer, we speculated that RPPH1 played a significant role in tumour biology." (PMID 29200969, 2017). "Correlation analysis revealed a high value of R2 = 0.8431, indicating that miR-122 may possibly be the target binding gene of RPPH1 in breast cancer." (PMID 29200969, 2017). "In this study, we intended to explore the interactions of RPPH1 in breast cancer." (PMID 29200969, 2017). "Thus, RPPH1 levels were found increased in breast cancer tissues and cell lines." (PMID 32611613, 2020). "Taken together, RPPH1 more likely functions as an oncogene in human diseases rather than just a well-known RNA subunit of RNase P involved in regulating tRNA (transfer ribonucleic acid) maturation, and plays important roles in the biological and pathological processes of breast cancer and AML." (PMID 31645843, 2019). "Based on the qPCR results in the RPPH1 function cell models, we may infer that RPPH1 promoted breast cancer cell proliferation and cell cycle progression through down-regulation of micro-RNA 122 and influence the expression of ADAM10, PKM2, NOD2 and IGF1R genes." (PMID 29200969, 2017). "We then determined whether RPPH1 expression influenced the proliferation of breast cancer cells." (PMID 29200969, 2017). "In addition, qPCR detected high expression of RPPH1 in four kinds of breast cancer cell lines." (PMID 29200969, 2017). "Reduced expression of BLACAT1 in HNSCC; MALAT1, NEAT1 and PVT1 in NPC; FAM201A, PVT1 and LINC00857 in NSCLC; LINC00473, CCAT2and Rpph1 in EC; HOTAIR and LINC00958 in CRC; AFAP1-AS1 and LINC00511 in breast cancer were correlated with radiosensitivity." (PMID 36323697, 2022). "In other words, silencing lncRNA RPPH1 downregulates PKM2 gene expression by an indirect attachment with miR-122, which inhibits breast cancer cell proliferation and tumorigenesis and implies lncRNA RPPH1′s importance as a promising therapeutic target." (PMID 36230935, 2022). "We focus on the application of highly sensitive technology such as digital PCR (dPCR) to differentiate breast cancer (BC) patients and controls by quantifying regions of PUM1 and RPPH1 (RNase P) in plasma samples." (PMID 33522650, 2021). "In agreement with our findings in breast cancer tissues, we found that the MCF-7 and MDA-MB-231 cell lines exhibited high RPPH1 expression, compared with the HBL-100 cell line." (PMID 29200969, 2017). "While RPPH1 over-expression promoted cell cycle and proliferation and increased colony formation of human breast cancer cell lines MCF-7 and MDA-MB-231, knockdown of RPPH1 significantly inhibited cell proliferation in both MCF-7 and MDA-MB-231 cells (Zhang and Tang, 2017)." (PMID 31645843, 2019). "Recent studies revealed that RPPH1 is upregulated in gastric cancer and breast cancer, but the mechanisms are not yet clear." (PMID 31685807, 2019). "First, RPPH1 expression in chosen representative breast cancer cell lines was investigated and compared with that in non-tumour breast cell lines." (PMID 29200969, 2017).
gastric cancer (6 papers, 2017 to 2023). A primary or metastatic malignant neoplasm involving the stomach. "For example, upregulation of RPPH1 in gastric cancer predicted the poor prognosis of patients and promoted cell proliferation and migration." (PMID 37291525, 2023). "For its clinical significance, RPPH1 was reported to indicate poor prognosis of gastric cancer patients and promotes the development of non-small cell lung cancer.." (PMID 37291525, 2023). "RPPH1 also predicts poor prognosis and regulates cell proliferation and migration by repressing P21 expression in gastric cancer." (PMID 36619232, 2023). "Surprisingly, Rpph1 was differentially expressed in gastric cancer and neocortical tissues of seizure patients." (PMID 28223918, 2017). "Previous studies reported that RPPH1 was up-regulated in gastric cancer specimens." (PMID 31750237, 2019). "Rpph1 has also been used to as an internal control for RNA quantification However, recent deep sequencing studies showed that Rpph1 was up-regulated in the human gastric cancer tissues and in the neocortex of seizure patients, as well as in cortical samples from the APPswe/PS1ΔE9 mice." (PMID 28223918, 2017).
diabetic nephropathy (4 papers, 2019 to 2024). "These included RPPH1, an RNA component of the RNase P ribonucleoprotein, which has been linked to mesangial cell inflammation and proliferation in diabetic nephropathy." (PMID 37547464, 2023). "Rpph1 was shown to bind Gal-3, a biomarker of diabetic nephropathy, which itself was increased in diseased renal tissue and enhanced mesangial cells proliferation." (PMID 32611613, 2020). "Rpph1 was also up-regulated in renal tissue of mice with diabetic nephropathy; in fact it was the most up-regulated long noncoding RNA." (PMID 32611613, 2020). "RPPH1 promoted mesangial cell inflammation and proliferation in diabetic nephropathy." (PMID 37547464, 2023).
acute myeloid leukemia (3 papers, 2019 to 2023). Acute myeloid leukemia (AML) is a group of neoplasms arising from precursor cells committed to the myeloid cell-line differentiation. "We aimed to explore the functions of RPPH1 in the pathogenesis of acute myeloid leukemia (AML) and the underlying molecular mechanisms." (PMID 31645843, 2019). "lncRNA RPPH1 acts as an oncogene also in BC and acute myeloid leukemia (AML)." (PMID 33522932, 2021).
hepatocellular carcinoma (3 papers, 2023 to 2025). A malignant tumor that arises from hepatocytes. "Circ0515, a newly identified circRNA derived primarily from the RPPH1 gene and located at chr14: 20811305-20811534, has been shown to be highly expressed in hepatocellular carcinoma." (PMID 40617805, 2025). "More importantly, we showed that RPPH1 supports cell viability and metastasis by activating the Wnt1/β-catenin pathway by serving as a molecular sponge for miR-122 in hepatocellular carcinoma." (PMID 36619232, 2023). "This study aimed to explore the role of lncRNA RPPH1 in hepatocellular carcinoma." (PMID 36619232, 2023).
lung carcinoma (3 papers, 2021 to 2023). "RPPH1 downregulation suppresses the invasive ability of lung cancer cells, while RPPH1 overexpression shows the opposite effects by sponging miR-326 expression." (PMID 37190145, 2023). "RPPH1 shows more unique expression in lung cancer than normal cells, contributing to cisplatin resistance." (PMID 37190145, 2023). "Three differentially expressed lncRNAs listed in the CDEGs, namely, ILF3-AS1, JPX, and RPPH1, have already been reported to be involved in the progression of lung cancer by affecting cell proliferation and migration." (PMID 34336829, 2021).
bladder cancer (2 papers, 2024). "For example, Rpph1 is enriched in bladder cancer and linked to immune-related pathways, such as IL-1, TNF-α, Il-17 signaling, and M2 macrophage polarization." (PMID 39769061, 2024). "In this study, we observed that hsa_circ_0000520, derived from the lncRNA RPPH1, was downregulated in bladder cancer cell lines and tissues." (PMID 39237880, 2024).
Alzheimer disease (1 paper, 2019). A progressive, neurodegenerative disease characterized by loss of function and death of nerve cells in several areas of the brain leading to loss of cognitive function such as memory and language. "A previous study demonstrated that the pathway of RPPH1/miR-330-5p/CDC42 is involved in the compensatory behavior of brain neurons to combat synaptic loss during the pathogenesis of Alzheimer's disease." (PMID 31645843, 2019).
chronic gastritis (1 paper, 2025). Inflammation of the stomach that is chronic in nature. "Serum EV lncRNA RMRP, RPPH1, and linc-ROR were significantly higher in patients with GC than in those with chronic gastritis, atypical hyperplasia, or healthy control (all P < 0.05)." (PMID 39925803, 2025).
colon cancer (1 paper, 2018). "We noted that 11 lncRNAs, SCARNA10, RPPH1, LINC01419, ERVH48-1, RMRP,CH507-513H4.3, MIR205HG, CH507-513H4.6, LINC00400, RP11-774D14.1 and AC006050.2, were also differentially expressed in colon cancer samples compared with the normal samples." (PMID 29420609, 2018).
lung adenocarcinoma (1 paper, 2023). A carcinoma that arises from the lung and is characterized by the presence of malignant glandular epithelial cells. "The copy numbers of both the target (CYP2C8, CYP3A4) and the reference genes (ALB, B2M, BCKDHA, F5, CD36, MPO, TBP, RPPH1) established in primary lung adenocarcinoma by the qPCR-based method were congruent with those determined by next-generation sequencing (for 10 genes, slope = 0.9498, r2 = 0.72)." (PMID 37686184, 2023).
lymph node metastasis (1 paper, 2025). "However, this work did not observe a significant association between circ-RPPH1 and TNM staging and lymph node metastasis, possibly because of the small sample size." (PMID 40346652, 2025). "However, the mechanism of circ-RPPH1/EIF4 A3/regulating E-cadherin expression needs further study.The shortcomings of this study, Sample Size and Clinical Correlations: The lack of association between circ-RPPH1 and TNM stage/lymph node metastasis may reflect insufficient statistical power." (PMID 40346652, 2025).
pneumonia (1 paper, 2023). An acute, acute and chronic, or chronic inflammation focally or diffusely affecting the lung parenchyma, caused by an infection in one or both of the lungs (by bacteria, viruses, fungi, or mycoplasma.). "LncRNA RPPH1 (RPPH1) was found to be downregulated in severe pneumonia." (PMID 37291525, 2023). "Therefore, the dysregulation of RPPH1 in severe pneumonia was also speculated to serve as a biomarker of SCAP for its early detection and prognosis prediction." (PMID 37291525, 2023).
prostate carcinoma (1 paper, 2022). A carcinoma that arises from epithelial cells of the prostate gland. "On the contrary, PTGS2, CLDN1, and RPPH1 are negatively correlated with the prognosis of prostate cancer." (PMID 35813821, 2022).
viral infection (1 paper, 2025). "As shown for 7SL RNA, RPPH1 can act as a direct ligand for RIG-1 and its increased expression in the cytoplasm induces the RIG-1-mediated IFN response during viral infection." (PMID 40510596, 2025).